AGAP9 (ArfGAP with GTPase domain, ankyrin repeat and PH domain 9)
Description:
Putative GTPase-activating protein.
Synonyms: AGAP-9; CTGLF6; bA301J7.2; FLJ00312
Tractability: No criterion of Open Targets' tractability assessment is met for any kind of drug.
Gene: Protein-coding gene on chromosome 10 (47,501,854 to 47,523,638, reverse strand). Ensembl gene ENSG00000204172.
Gene Ontology:
Molecular function: GTPase activator activity; GTPase activity
Genetic constraint (gnomAD): Loss-of-function variants: 20 observed, 35.32 expected, observed/expected ratio (o/e) 0.57, 90% interval 0.4 to 0.82. The synonymous counts are far from expectation, so gnomAD's model fits this gene poorly and the ratio says little. Missense variants: 291 observed, 560.18 expected, observed/expected ratio (o/e) 0.52, 90% interval 0.47 to 0.57. Synonymous variants: 116 observed, 213.72 expected, observed/expected ratio (o/e) 0.54, 90% interval 0.47 to 0.63.
Homologues: Paralogues in human: AGAP4 (95% identical), AGAP5 (95% identical), AGAP6 (94% identical), AGAP1 (59% identical), AGAP3 (46% identical), AGAP2 (40% identical), ACAP3 (18% identical), ACAP2 (17% identical), ACAP1 (16% identical), ASAP1 (16% identical), ASAP2 (16% identical), ASAP3 (15% identical), and 16 more.
Diseases named in the same sentence as AGAP9 in open-access papers:
AGAP9 is named in the same sentence as 3 diseases in open-access papers, as found by Europe PMC text mining. Sharing a sentence is not in itself a finding about the gene and the disease. The quoted sentences say what the papers report.
colon cancer (1 paper, 2023). "In the present study, a four-gene signature of colon cancer, consisting of HSF4, UPK3B, ZNF767P, and AGAP9, was generated and validated." (PMID 36681801, 2023).
AGAP9 also shares sentences with these, for which no sentence is quoted: colon adenocarcinoma (1 paper); Esotropia (1).